APOE (apolipoprotein E)
Diseases named in the same sentence as APOE in open-access papers (continued):
Sharing a sentence is not in itself a finding about the gene and the disease.
endotoxemia (14 papers, 2010 to 2024). "ApoE knockout mice are highly susceptible to endotoxemia and Klebsiella pneumoniae infection due to their inability to neutralize LPS." (PMID 37533741, 2023). "Recent studies have indicated that APOE knockout mice are highly susceptible to endotoxemia, Listeria monocytogenes and Klebsiella pneumoniae infection." (PMID 32978453, 2020). "APOE knockout mice as compared to normolipidemic wild-type mice display an enhanced susceptibility to endotoxemia." (PMID 24265824, 2013). "Our studies show that adrenalectomy induces leukocytosis and enhances the susceptibility for endotoxemia in APOE knockout mice." (PMID 24265824, 2013). "In conclusion, our studies show that adrenalectomy induces leukocytosis and enhances the susceptibility for endotoxemia in APOE knockout mice." (PMID 24265824, 2013). "ApoE protects against bacterial LPS-induced lethality, and recombinant apoE shows potential therapeutic application in protecting against LPS-induced endotoxemia." (PMID 37533741, 2023). "It thus seems that in APOE knockout mice glucocorticoids do efficiently execute their anti-inflammatory function and thereby protect against induction of (fatal) endotoxemia." (PMID 24265824, 2013). "ApoE- enriched emulsion can shift bacterial LPS from liver Kupffer cells to hepatocytes, therefore reducing LPS-derived endotoxemia (binds at ratio of 1:2 LPS molecules)." (PMID 22524518, 2012). "Consistent with its ability to facilitate the clearance of TG-rich lipoproteins by the liver, apoE has been shown to both redirect LPS from Kupffer cells to hepatocytes, and protect against endotoxemia in rats." (PMID 20953368, 2010). "Interestingly, A. muciniphila was reduced by D. desulfuricans treatment, which can partially mediate D. desulfuricans effects since A. muciniphila was shown to reduce plaque and prevent endotoxemia in ApoE−/− mice." (PMID 39203469, 2024). "To clarify whether the pharmacological benefits of sivelestat is dependent on lowering endotoxemia, we subcutaneously injected lipopolysaccharides (LPS) into sivelestat-treated ApoE-/- mice." (PMID 35444551, 2022). "Studies using APOE deficient mice confirmed the role of APOE in host susceptibility to endotoxemia and Klebsiella pneumoniae infection, while transgenic mice expressing human APOE3 and APOE4 genes revealed an isoform-specific effect of APOE on the proinflammatory response to lipopolysaccharide." (PMID 24586873, 2014). "ApoE knockout mice are also more susceptible to endotoxemia and gram-negative infections despite their elevated plasma lipid concentrations." (PMID 20953368, 2010). "In addition, intravenous apoE protected against endotoxemia in vivo, further suggesting anti-infective properties." (PMID 20953368, 2010). "Moreover, apolipoprotein E (apoE), a component of triglyceride-rich lipoproteins, has been shown to be protective in endotoxemia and gram-negative infections in addition to its well-known role in lipid metabolism." (PMID 20953368, 2010).
non-alcoholic steatohepatitis (14 papers, 2015 to 2025). "For instance, APOE polymorphisms are significantly associated with non-alcoholic steatohepatitis, particularly the a APOE ε3 genotype." (PMID 40301749, 2025).
anemia (13 papers, 2008 to 2024). A reduction in the number of red blood cells, the amount of hemoglobin, and/or the volume of packed red blood cells. "It is possible that the PFE1590w – ApoE interaction is important for cerebral malaria and severe anaemia, and thus individuals carrying ApoE ε3 and ε4 alleles are more likely to develop these symptoms." (PMID 18937849, 2008). "We demonstrated that VLDL and ApoE play key roles in the response to acute anemia; the addition of recombinant ApoE increased the erythroid output of HSCs, whereas HSCs of Apoe−/− mice did not exhibit enhanced erythroid potential." (PMID 39284836, 2024). "Here, the authors show that acute anemia triggers hematopoietic stem cell proliferation and guides differentiation towards erythroid cells in a process mediated by apolipoprotein E." (PMID 39284836, 2024). "The most significant results were associations between cognitive dysfunctions and genetic polymorphisms, including APOE-4 and COMT-Val; increased plasma levels of the pro-inflammatory cytokine, IL-6; anemia; and hemoglobin levels during chemotherapy." (PMID 28377717, 2017). "As both the concentration of VLDL-TG and the size of VLDL significantly decreased upon PHZ injection, we wondered whether ApoE expression increased upon acute anemia induction." (PMID 39284836, 2024). "In severe anemia, lipoprotein profiles largely change and the concentration of ApoE increases." (PMID 39284836, 2024). "Importantly, epigenetic changes upon acute anemia induction were selectively observed in VldlrhighHSCs; this subfraction of HSCs starts differentiating upon ApoE stimulation, while the counter fraction (VldlrlowHSCs) remained undifferentiated to maintain the HSC pool." (PMID 39284836, 2024). "Although the ApoE−/− mice were significantly resistant to ECM, their parasitemia increased significantly and they eventually succumbed to hyperparasitemia and severe anemia." (PMID 27647324, 2016). "There were less APOE ε4 carriers in anaemia group (6.0%) than non-anaemia group (18.1%)." (PMID 34794413, 2021).
Apathy (13 papers, 2020 to 2025). Apathy is a quantitative reduction of interest, motivation and the initiation and persistence of goal-directed behavior, where often the accompanying emotions, thoughts, and social interactions are also diminished. "Most notably, the main finding of greater risk of conversion with apathy and with antidepressant use was present across both APOE ε4 carriers (HR = 4.24, 95%CI = 2.38-7.53, P < 0.001) and non-carriers (HR = 2.82, 95%CI = 1.51-5.28, P = 0.001)." (PMID 40227643, 2025). "Apathy and APOE ε4 were associated with increased risk of conversion along the CN-MCI-ADD continuum." (PMID 40227643, 2025). "In summary, we found combined effects of apathy and APOE ε4 status were associated with increased risk of conversion from CN to MCI and MCI to ADD." (PMID 40227643, 2025). "Individuals with an APOE ε33 genotype and who did endorse apathy had an 84% increased risk of conversion compared to their non-apathetic counterparts (HR = 1.84, 95%CI = 1.08-3.13, P = 0.02)." (PMID 40227643, 2025). "This study aimed to identify the associations of apathy, APOE ε4 allele status, and antidepressant medication use with progression from CN to MCI, and from MCI to ADD." (PMID 40227643, 2025). "We expected to see increased risk of conversion to MCI and ADD in individuals with apathy and at least 1 APOE ε4 allele." (PMID 40227643, 2025). "As 2 APOE ε4 alleles are associated with greater risk for ADD than 1 allele, parsing out dose-related effects of APOE ε4 on apathy and progression risk in larger samples is warranted for future work." (PMID 40227643, 2025). "Here, we aimed to characterize the effects of apathy, APOE genotype, and antidepressant use on risk of conversion from CN to MCI, and from MCI to ADD." (PMID 40227643, 2025). "A total of 68 cortexes, IVC, age, education years, sex, and APOE ε4 status were included as covariables to identify risk regions of Aβ deposition for apathy conversion through the Cox proportional hazards model." (PMID 34663799, 2021). "In another study, apathy and APOE ε4 were both associated with the reduced levels of brain-derived neurotrophic factor (BDNF) in AD patients, which was considered as a pathogenic event of AD." (PMID 33041262, 2020). "Previous study showed the evidence that both APOE ε4 and apathy increased the risk of AD, and the hazard of developing AD was almost eleven times higher for ε4 carriers with apathy." (PMID 33041262, 2020). "Additionally, individuals with apathy and an APOE ε33 genotype had a 52% increased risk of conversion (HR = 1.52, 95%CI = 1.06-2.19)." (PMID 40227643, 2025). "We first examined whether apathy interacts with the genetic risk factor for conversion, APOE ε4 allele possession." (PMID 40227643, 2025). "Moreover, subjects with higher frontal Aβ deposition had a higher risk for apathy conversion with age, education years, sex, APOE, and ICV as covariables (Fig. 4A3)." (PMID 34663799, 2021). "Interestingly, a synergistic interaction between some NPS (depression or apathy) and APOE-Ɛ4 has been found to increase the risk of dementia." (PMID 33742011, 2021). "We suspected that ApoE ε4 and apathy might share some common pathogenic mechanisms underlying the development of AD, such as reduced BDNF level, but directly related to each other." (PMID 33041262, 2020). "Cox proportional hazards analyses examined the combined effects of apathy, APOE ε4 genotype, and antidepressant use on conversion from CN to MCI and from MCI to ADD." (PMID 40227643, 2025). "Overall, results demonstrated significant three-factor interactions in accordance with the main findings of the two-factor Apathy + APOE ε4 and Apathy + Antidepressant analyses." (PMID 40227643, 2025). "Our findings, therefore, introduce a plausible novel link between apathy + APOE ε4 and progression from CN to MCI, specific to individuals with amnestic MCI (ADD prodrome)." (PMID 40227643, 2025).
Apathy (continued). "And the patients with DLB + APOE ε4 (+) were presented more delusions (p = 0.005) and apathy (p = 0.007) than patients with PDD + APOE ε4 (+)." (PMID 36123648, 2022). "The APOE ε4 allele was more common in DLB than PDD (29.9% vs. 7.0%, p < 0.001), and the patients with DLB + APOE ε4 (+) were presented more delusions (p = 0.005) and apathy (p = 0.007) than patients with PDD + APOE ε4 (+)." (PMID 36123648, 2022). "Compared with the 468 Aβ− elderly, the 589 Aβ+ elderly showed faster elevation of apathy severity (β = 0.083, p < 0.0001), after controlling the age, education years, sex, and APOE ε4 status (n = 2008 person-times in total)." (PMID 34663799, 2021). "In our study, apathy was the only behavioral condition with a significant result in a multiplicative interaction with APOE ɛ4, but its effect has to be interpreted in terms of a reduction in the risk rate." (PMID 33208795, 2020). "A 3-fold increase in risk of conversion was revealed for individuals without apathy, on an antidepressant medication, and with the possession of an APOE ε4 allele (HR = 3.50, 95%CI = 1.10-11.48, P = 0.038)." (PMID 40227643, 2025). "The reference group was CN individuals without apathy, not on an antidepressant medication, and without an APOE ε4 allele." (PMID 40227643, 2025). "In the CN to MCI group, participants with apathy, not on an antidepressant, and no APOE ε4 allele, converted 2-times faster than their non-apathetic counterparts who were not on an antidepressant and non-carriers (reference group)." (PMID 40227643, 2025). "APOE ε4 carriers without apathy had a 72% increase in risk of conversion (HR = 1.72, 95%CI = 1.24-2.38, P = 0.001)." (PMID 40227643, 2025). "An increased risk of conversion for individuals APOE ε2 carriers with apathy (HR = 2.08, 95%CI = 0.62-7.03, P = 0.24), and attenuated risk for APOE ε2 carriers without apathy (HR = 0.57, 95%CI = 0.22-1.44, P = 0.23) was found to be non-significant." (PMID 40227643, 2025). "Participants with apathy tended to be male and APOE ε4 carrier." (PMID 34663799, 2021). "Moreover, individuals with apathy showed faster Aβ deposition in cortical regions including the frontal lobe, left mOFC, and right POC after controlling the age, education years, sex, APOE ε4 status, and ICV (D1–D3)." (PMID 34663799, 2021). "In this investigation, the frequency of all ApoE genotypes, including ε2/ ε2, ε2/ ε3, ε2/ ε4, ε3/ ε3, ε3/ ε4, and ε4/ ε4, was not significantly different between the AD-A and AD-NA groups (P>0.05), which demonstrated that ApoE genotype had no influence on apathy in AD patients." (PMID 33041262, 2020).
colon cancer (13 papers, 2009 to 2025). "APOE-ε3 has also shown an inverse correlation between concentration and colon cancer; a deficiency in APOE-ε3 leads to colon cancer, which has been especially observed populations over 50 years of age." (PMID 38067270, 2023). "Colocalization and pathway enrichment analysis suggested that LBD and colon cancer possibly shared causal variants (nearby gene APOE), and ERBB4 signaling and lipid metabolism may mediate the causal association between LBD and colon cancer." (PMID 39170445, 2024). "Moreover, colocalization analysis suggested that LBD and colon cancer possibly shared causal variants and had one shared locus (rs769449, nearby gene APOE)." (PMID 39170445, 2024). "Overall, our results suggest an important role for ApoE in colon homoeostasis and integrity and predict that ApoE deficiency may be a risk factor for chronic diseases such as colitis and colon cancer." (PMID 27538678, 2016). "Other factors that may determine the potential association between the genotypes of APOE and colonic cancer include racial variation, genetic background, diet, and physical training, which have likely led to a discrepancy in findings on the carcinogenicity of the allele ε4." (PMID 38067270, 2023). "Conversely, in cellular studies, overexpression of APOE enhanced proliferation and migration in colon cancer HCT-116 and HCT-8 cells." (PMID 40149482, 2025). "Regional Manhattan plots examined the association of all SNPs ±50 kb from the top SNP for LBD (rs769449, nearby gene APOE) for their association with LBD and with colon cancer risk." (PMID 39170445, 2024). "In vitro studies suggest that treatment of colon cancer cell line HT29 with ApoE enhanced cell polarity by translocating β-catenin from the cytoplasm to cell–cell adhesion sites." (PMID 19455140, 2009). "An age-specific association was also observed for colon cancer but not for rectal cancer in case of apolipoprotein E (apoE) polymorphism." (PMID 20920350, 2010). "Colocalization analysis suggested that AD and colon cancer shared no causal variants (PP.H4 = 8.1 %), whereas LBD and colon cancer possibly shared causal variants (PP.H4 = 61.0 %) and had one shared locus (rs769449, nearby gene APOE)." (PMID 39170445, 2024).
lung fibrosis (13 papers, 2015 to 2025). "ApoE-deficient MA female mice also demonstrated increased pulmonary fibrosis compared to young female mice as shown by Masson trichrome staining of lung sections." (PMID 28344760, 2017). "ApoE-deficient MA female mice manifested increased peripheral pulmonary artery muscularization and pulmonary fibrosis." (PMID 28344760, 2017). "In vivo, β-glucan-elicited ApoE+CD11b+ AMs limited the bacterial burden of Legionella pneumophilia after infection and improved the disease outcome in vivo and ex vivo in a murine lung fibrosis model." (PMID 38671323, 2024). "Apolipoprotein E (ApoE) is highly expressed in fibrosis stage of BLM-induced pulmonary fibrosis mice." (PMID 35111363, 2022). "Others have recently reported a beneficial role for Mo-AM-derived apolipoprotein E (ApoE) for the resolution of bleomycin-induced pulmonary fibrosis." (PMID 34202229, 2021). "Furthermore, the role of ApoE in modulating fibroblast activity and resolving fibrosis has been demonstrated in pulmonary fibrosis models, where ApoE promoted the resolution of fibrosis by binding to collagen and mediating its phagocytosis." (PMID 40542610, 2025). "Finally, β-glucan-induced macrophages upregulate ApoE, a protein demonstrated to be part of various disease-specific MoMac gene signatures, for example, during influenza infection, lung fibrosis or obesity." (PMID 38671323, 2024). "In addition, HFD exacerbates bleomycin‐induced pulmonary fibrosis in wild‐type (WT) and ApoE knockout (ApoE−/−) mice." (PMID 37345264, 2023). "Besides, a single dose of BLM instillation induces more severe pulmonary fibrosis in the ApoE-/- mice and the fibrosis develops progressively and irreversibly." (PMID 35111363, 2022). "Egr2fl/fl mice failed to repair the lung after injury, a finding consistent with an older study using non-specific, clodronate-mediated depletion of lung macrophages and a recent study implicating ApoE-producing, monocyte-derived alveolar macrophages in lung fibrosis resolution." (PMID 34797692, 2021). "To determine whether downstream ApoE is critical for miR-130/301-induced fibrosis, we attempted to prevent lung fibrosis in bleomycin-exposed mice via treatment with a pharmacological activator of ApoE13, the liver-X nuclear hormone receptor agonist GW3965." (PMID 26667495, 2015). "The recent findings from single-cell RNA-Seq data from mice and human lung fibrosis revealed the presence of a distinct profibrotic macrophage subtype in the fibrotic lung, with a higher level of CHI3L1, CHIT1, APOE, and integrins." (PMID 36626225, 2023). "In pulmonary fibrosis, alveolar epithelial dysregulation (SFTPC↓, KRT17↑) and macrophage polarization (SPP1, CHI3L1) are observed along with impaired regeneration driven by altered signaling (TGF-β, APOE, YAP1, TEAD)." (PMID 40563563, 2025). "Furthermore, consistent with the direct down-regulation of the associated factors peroxisome proliferator-activated receptor gamma (PPARγ), apolipoprotein E (APOE) and the apolipoprotein E receptor LRP8 by miR-130/301 in PH 9, both Pparγ and Lrp8 were decreased in pulmonary fibrosis." (PMID 26667495, 2015).
pulmonary hypertension (13 papers, 2011 to 2025). Increased pressure within the pulmonary circulation due to lung or heart disorder. "Recent reports have suggested that insulin resistance might also be associated with pulmonary hypertension in humans and in the ApoE deficient mice." (PMID 21513515, 2011). "Recent trends in this cluster have shifted toward “pulmonary arterial hypertension,” “apolipoprotein E,” and “myofibroblast differentiation,” indicating a mechanistic focus on vascular remodeling and fibrogenesis." (PMID 40625354, 2025). "It has been well documented that the ApoE−/− mice on a high-fat diet developed pulmonary arterial hypertension; those on a Paigen diet exhibited more severe pulmonary hypertension." (PMID 25975841, 2015). "In addition, apoE has both protective and anti-inflammatory properties in the setting of lung disease, reducing primary pulmonary hypertension." (PMID 35359998, 2022). "ApoE knockout mice also develop pulmonary hypertension on high fat diet." (PMID 28344760, 2017). "Patients with pulmonary hypertension (PH) have reduced expression of ApoE in lung tissue." (PMID 28344760, 2017). "Interestingly, patients with pulmonary arterial hypertension (PAH) have reduced expression of ApoE in lung tissue." (PMID 28344760, 2017). "Pulmonary ApoE expression is reduced in patients with idiopathic pulmonary arterial hypertension, and in experimental models ApoE inhibits the proliferation of pulmonary artery smooth muscle cells and protects against the development of pulmonary arterial hypertension." (PMID 28624389, 2017).